RARA (retinoic acid receptor alpha)
Diseases named in the same sentence as RARA in open-access papers (continued):
Sharing a sentence is not in itself a finding about the gene and the disease.
breast carcinoma (continued). "In immortalized mammary tumor cells, it is interesting to notice that ATRA exposure inhibits EMT, while RARα overexpression exerts an opposite effect on the process." (PMID 38360674, 2024). "RARα is necessary for ERE-mediated transcription and proliferation in breast cancer cells and has significantly overlapping target genes with ERα." (PMID 36534918, 2023). "Using human breast cancer cells transfected with MAD1 SID or treated with the MAD SID peptide, we observed a dissociation of MAD1, RARα and RARβ from Sin3A in a coimmunoprecipitation assay." (PMID 35406744, 2022). "As RARα mediates the anti-proliferative action of ATRA in breast cancer cells, we exposed SK-BR-3 cells to ATRA, AM580 (RARα-agonist), UVI2003 (RARβ-agonist) and BMS961 (RARγ-agonist)." (PMID 32384653, 2020). "The expression of both MR and RARB was higher in normal breast tissues and decreased in breast cancers while the expression of RARG and RARA was high and largely invariant in both sample cohorts." (PMID 33148314, 2020). "In turn, RARα drives the transcription of CRABP2 except for MDA-MB-468 cells, which belongs to ER− breast cancer cells." (PMID 31419991, 2019). "We considered breast cancer SK-BR-3 and MCF-7 cells, lung cancer A-549 cells as well as APL-derived and PML-RARα+NB4 blasts which synthesize measurable levels of S100A3 and RARα." (PMID 30532072, 2019). "To identify novel RARα interacting proteins, we stably transfected a FLAG-tagged RARα (FLAG-RARα) plasmid and the corresponding void vector in ATRA-resistant MDA-MB-453 breast cancer cells, generating RA-453 and FL-453 cells, respectively." (PMID 30532072, 2019). "All these results indicate that the ATRA-induced decrease in CLs and the associated reduction in mitochondrial membrane microviscosity are dependent on RARα, which is a crucial determinant of ATRA anti-tumor activity in breast cancer." (PMID 31665044, 2019). "In ATRA-sensitive breast cancer cells, S100A3 binds to RARα in basal conditions and binding is reduced by the retinoid." (PMID 30532072, 2019). "In bladder and breast cancer, two common receptors are part of the input layer: (i) EGFR and (ii) the retinoic acid receptor alpha (RARA)." (PMID 28775339, 2017). "SKBR3-cells, characterized by ERBB2/RARA co-amplification, represent a subgroup of HER2+ breast-cancers sensitive to all-trans retinoic acid (ATRA) and Lapatinib." (PMID 25961594, 2015). "Yang & al, 1999 have shown that RARα expression is lower in normal breast cells and ER-negative breast cancer cells (MDA MB 231 and MDA MB 435), compared to ER-positive breast cancer cells (MCF7 and T47D)." (PMID 19442290, 2009). "Indeed, in both cell cultures and mouse models of mammary tumors, ATRA-induced growth inhibition is recapitulated only by the RARα agonist AM580, as RARβ and RARγ agonists are generally ineffective in terms of anti-proliferative effects." (PMID 38360674, 2024). "Although GATA binding protein 3 (GATA3) and retinoic acid receptor alpha (RARα) were also identified as ERα cooperative factors in breast cancer cells, these were not identified as crucial players in our investigations on ERα-driven SEs." (PMID 32120995, 2020). "Early analysis on breast cancer cell lines showed that CRABP-II content in the cell was positively related to ATRA-growth inhibition, and that the ectopic CRABP-II enhanced ATRA action, and evidence showed that RARα drives CRABP-II transcription." (PMID 32012980, 2020). "To establish whether ATRA modulates the expression of RARα, RARβ and RARγ, we exposed six TNBC and six retinoid-sensitive Luminal breast cancer cell lines to ATRA (1 μM) for 24 h." (PMID 33081033, 2020).
breast carcinoma (continued). "Thus, ligand-dependent activation of RARα seems to be the primary determinant of ATRA-dependent action in TNBC cells, as previously observed in the case of luminal breast cancer cell lines." (PMID 33081033, 2020). "According to the Cancer Genome Atlas (TCGA) breast cancer is not characterized by RARA fusion proteins." (PMID 30678048, 2019). "In addition, RARα, another ATRA target, has been indicated to play a role in tamoxifen resistance of breast cancer." (PMID 31867329, 2019). "In breast cancer cell lines, inhibition of endogenous RARα expression led to growth stimulation through a non-RAR-mediated signaling pathway." (PMID 29301374, 2018). "Here we show that anticancer and cancer-promoting RA actions in breast cancer have roots in a mechanism of mammary epithelial cell morphogenesis that involves both transcriptional (epigenetic) and non-transcriptional RARα (RARA) functions." (PMID 27894085, 2016). "In breast cancer cells it is not always possible to pinpoint “the” factor(s) that, by inhibiting RARA transcriptional function, make RA exert a cancer-promoting action." (PMID 27894085, 2016). "In addition, RARα is a biomarker of ATRA sensitivity and the major target for retinoids in breast cancer." (PMID 25888236, 2015). "Thus, RARα is the predominant mediator not only of the anti-proliferative, but also of the transcriptional effects afforded by ATRA in the two breast cancer cells." (PMID 25888236, 2015). "The estrogen receptor-negative and HER2+SKBR3 cell line is representative of a recently identified breast cancer subtype characterized by co-amplification of the genes coding for the HER2 membrane receptor (ERBB2) and the RARα nuclear retinoid receptor (RARA), respectively." (PMID 25961594, 2015). "Although more highly expressed in ERα-positive breast cancer, high-level RARα expression was also evident in ERα-negative tumours." (PMID 26280373, 2015). "Likewise, Retinoic acid receptor alpha, CD44 and deltaEF1 had been reported to be involved in the development of tamoxifen resistance in breast cancer." (PMID 24622579, 2014). "Yet, the mechanisms of action by which the RARA agonists or antagonists carry out a repressive effect in breast cancer are not entirely clear." (PMID 23192763, 2013). "RA-induced proliferation in the absence of a functional RARα signaling is not breast cancer cell context-specific and can occur both in transformed and untransformed cells (unpublished observations)." (PMID 17786207, 2007). "While we found that RARα agonists can inhibit CMA in cancer cells, both ATRA and AM580 are also capable of inducing macroautophagy in certain conditions, including breast cancer and NSCLC (Fig. EV2F–H shows increased number of autophagic vesicles and autophagic flux with either treatment)." (PMID 40490560, 2025). "Since activation of RARα induced autophagic flux in RA-sensitive but not in RA-resistant breast cancer cells, we asked whether RARαS77A could bypass RARα activation to induce autophagy in TNBC cells as well." (PMID 33902658, 2021). "Moreover, it was recently reported that RA-induced autophagy in breast cancer occurred through the activation of RARα; although we did not detect any significant changes in autophagy-related proteins in cells treated with RA alone." (PMID 29312596, 2017). "RARA, KRT19 and KRT20 amplification could be related to a more invasive breast cancer profile." (PMID 21288332, 2011). "To determine whether RARα mediates other ATRA-dependent responses of relevance for the anti-tumor activity of the retinoid, we measured single-cell random motility, as the process is a determinant of invasive/metastatic behavior and it is inhibited by ATRA in breast cancer cells." (PMID 25888236, 2015).
breast carcinoma (continued). "ATRA treatment of MCF-7 breast cancer cells reduced p11 but not p36 transcript and protein levels, thus indicating that ATRA can regulate p11 levels independently of PML/RARα and p36." (PMID 30206209, 2018). "For this reason, we chose a breast cancer cell line, MDA-MB-231, that does not express endogenous RARα (left) and the other downstream RA-regulated RAR genes, including RARβ2 (right)." (PMID 17786207, 2007). "Interestingly, this subtype of breast cancer shows a remarkable sensitivity to ATRA and RARα agonists, regardless of ER-positivity." (PMID 38360674, 2024). "Similarly, we observed lower RARα levels in tumours having high PRAME expression, suggesting that PRAME may also not act through RARα in breast cancer." (PMID 18648365, 2008).
lung cancer (22 papers, 2010 to 2025). A malignant neoplasm involving the lung. "The precise mechanism of how RARα over-expression increases risk of lung cancer-related tumor formation is presently unknown." (PMID 26462767, 2015). "Dysregulation of RARA and RARG has also been linked to cell survival and chemoresistance in other solid tumors, including skin and lung cancers." (PMID 41155227, 2025). "Considering the antioxidant and iron-modulating function, we validated the upregulated expression of RARA in mRNA and protein levels in four lung cancer cell lines." (PMID 38902322, 2024). "Lung cancer cell line, EBC-1, was shown to have upregulated RARα, and it was suggested that the growth inhibitory effects of vitamin A are linked to RARα mRNA expression." (PMID 35631448, 2022). "A study reported an in vitro increased expression of RARα and RARγ and reduced RARβ in lung carcinoma cell lines." (PMID 35631448, 2022). "The phosphorylation of these residues results in ubiquitin-mediated degradation of RARα, which is attributed to the low RARα expression in mouse lung cancer cells and insensitive to RA treatments." (PMID 34440929, 2021). "Another CpG site (cg19572487) maps to the retinoic acid receptor alpha gene, which plays an important role in various human cancers such as lung cancer." (PMID 32561690, 2020). "S100A3 knockdown decreases the amounts of RARα in breast- and lung cancer cells, inducing resistance to ATRA-dependent anti-proliferative/differentiating effects." (PMID 30532072, 2019). "Both RARα and RARγ were expressed in the examined human and murine lung cancer cell lines." (PMID 37689790, 2023). "RARα transactivation is activated by RA directly and is also regulated by Phosphorylation, and RARα phosphorylation is proved to contribute to inhibit RA signaling in lung cancers." (PMID 34721398, 2021). "How ATRA activates ERK in lung cancer cells is still unknown; there are reports that demonstrate that RARα mediates the rapid effects of ATRA in neuronal cells because it is present in membranes and activates ERK through the activation of the PI3K/Akt pathway." (PMID 26557664, 2015). "Additionally, recent reports have shown that Akt activation suppresses the transactivation of RARα in lung cancer cells." (PMID 23693014, 2013). "Given this and our prior work, it was hypothesized that an RARα antagonist (IRX6696) would cooperate with anti-PD-L1 therapy to elicit an anti-tumor response to a previously resistant syngeneic lung cancer by reducing CD38 expression and thereby conferring anti-neoplastic effects." (PMID 37689790, 2023). "ATRA-induced ERK activation in lung cancer cells may be mediated via RARα and PI3K." (PMID 26557664, 2015). "Our prior work reported that RARα agonist treatment can augment CD38 expression, leading to acquired lung cancer resistance in mice to anti-PD-L1 therapy." (PMID 37689790, 2023). "USP37 stabilizes MYC in lung cancer and the oncogenic fusion protein PLZF/RARA in Acute promyelocytic leukaemia (APL)." (PMID 37118828, 2023). "In this study, we demonstrate that treatment with ATRA can activate the ERK signaling pathway by a transcription-independent mechanism through a signaling cascade that involves RARα and PI3K, promoting growth, survival, and migration in lung cancer cells." (PMID 26557664, 2015). "Conversely, we showed that activating RARA with retinoids induced increased sensitivity by an order of magnitude to GSK461364A, an effect seen in all four lung cancer cell lines." (PMID 22248814, 2011). "Yet, RARα antagonist (IRX6696)-treatment with anti-PD-L1 did not repress syngeneic lung cancer growth." (PMID 37689790, 2023).
lung cancer (continued). "S100A3 knockdown reduced the amount of RARα in breast and lung cancer cells, and thus induced resistance to ATRA differentiation, suggesting that S100A3 is an important regulatory factor affecting breast and lung cancer cell differentiation." (PMID 34148033, 2021). "In a previous report, we demonstrated that, in lung cancer, RARα is responsible for mediating the nongenomic effects of ATRA by forming a signaling complex that is able to activate PI3K within the first few minutes after treatment with ATRA." (PMID 26557664, 2015). "There are no reports about RARα participation in nongenomic ERK activation by ATRA, and our results demonstrate that PI3K activation downregulates ERK activation through the ATRA/RARα signaling complex, which is responsible for mediating the rapid effects in lung cancer cells." (PMID 26557664, 2015).
acute leukemia (19 papers, 2010 to 2025). A clonal (malignant) hematopoietic disorder with an acute onset, affecting the bone marrow and the peripheral blood. "APL with PML::RARA fusion gene and AML with NPM1 mutation represent 2 distinct acute leukemias characterized by recurrent genetic abnormalities." (PMID 39432585, 2024). "The survivin mRNA expression positive rate in de novo and relapse groups, and PML/RARα fusion gene L-type positive groups, was obviously higher than those in remission period groups and was significantly lower than those in acute leukemia groups." (PMID 22550469, 2012). "Expression of the resulting PLZF-RARα and RARα-PLZF fusion proteins drives acute leukemia development by disrupting expression of both RARα and PLZF target genes." (PMID 21293049, 2010). "However, bone marrow aspirates testing for acute leukemia fusion genes by qPCR revealed the presence of the PML::RARA fusion." (PMID 39911670, 2024). "The survivin mRNA expression positive rate in the de novo and relapse groups, and PML/RARα fusion gene L-type positive groups was obviously higher than those in remission period groups (P < 0.05) and was obviously lower than those in acute leukemia grougs (P < 0.05, <0.001)." (PMID 22550469, 2012). "APL is characterized by the production of a fusion transcript of promyelocytic leukemia (PML) and retinoic acid receptor alpha (RARA) genes and is now the most frequently curable acute leukemia in adults." (PMID 39595968, 2024).
prostate carcinoma (16 papers, 2004 to 2025). A carcinoma that arises from epithelial cells of the prostate gland. "RARγ and RARα were increased significantly in high-grade prostate cancer, and a moderate to strong intensity of RARγ was seen in the nuclei of high-grade cells." (PMID 40362593, 2025). "The RARα selective antagonist AGN196996 was less effective than ATRA in preventing colony formation by the three prostate cancer cell lines." (PMID 40362593, 2025). "Silymarin inhibits the expression of ALDH1A1 in prostate cancer, which in turn inhibits the further activation of RARα and Ets1." (PMID 39055491, 2024). "Studies have shown a positive correlation between ALDH1A1 expression in prostate cancer tissue and Recombinant retinoic acid receptor alpha (RARα) and Erythroblastosis-twenty six 1 (Ets1)." (PMID 39055491, 2024). "ALDH1A1 promotes the invasion and metastasis of prostate cancer by activating RARα, which further activates Ets1." (PMID 39055491, 2024). "Most primary prostate cancer cells and the prostate cancer cell lines DU-145 and PC-3 express RARα and RARγ; the LNCaP cell line additionally expresses RARβ." (PMID 36768694, 2023). "Similar to PDAC cells, prostate cancer cells also express both RARα and RARγ, but the proliferation of tumor cells has been reported to depend only on RARγ." (PMID 37198667, 2023). "ALDH1A1 promoted invasion and metastasis of prostate cancer by activating the RARα, which further activates Ets1." (PMID 32984354, 2020). "Our results indicated that Silybin showed inhibition of prostate cancer and the mechanism was involving with downregulating ALDH1A1 expression, thereby inhibiting the activation of RARα and preventing the activation of Ets1 to inhibit the growth and invasion of prostate cancer." (PMID 32984354, 2020). "The responsibilities of estrogens and androgens have been clearly proven about breast and prostate cancers, while estrogen receptor-alpha (ERα) and retinoic acid receptor-alpha (RARα) have been extensively studied for their involvement in cancer risk, also with regard to oral cancers." (PMID 32684934, 2020). "For prostate cancer cell line cells, ATRA and the selective RARα antagonist AGN196996 were substantially less effective than AGN205728." (PMID 38928275, 2024). "Collectively, these results indicated that Silybin could inhibit prostate cancer by downregulating the expressions of ALDH1A1, RARα and Ets1 in vitro." (PMID 32984354, 2020). "The authors mentioned that these were because RARα, which requires approximately 100-times higher levels of ATRA than RARγ, was not sufficiently activated due to low levels of ATRA in prostate cancer tissues." (PMID 37198667, 2023).
myeloid leukemia (15 papers, 2011 to 2025). A clonal proliferation of myeloid cells and their precursors in the bone marrow, peripheral blood, and spleen. "GSK3 phosphorylation of certain proteins enhances their proteasomal degradation, and it is possible that this is the case for RARα as treatment of myeloid leukemia cells with GSK-3 inhibitors led to enhanced expression of RARα." (PMID 23213553, 2012). "Moreover, a study on myeloid leukemia cell lines showed that the most important isoform of RAR involved in the regulation of VDR transcription is RARα." (PMID 32916897, 2020). "Together, these results indicate a putative RA/c-Raf/GSK-3/RARα axis that is susceptible to RRD-251 and represents a novel regulatory pathway for RA differentiation that may extend its utility beyond APL to other myeloid leukemias." (PMID 27331409, 2016).
melanoma (14 papers, 1998 to 2025). A malignant, usually aggressive tumor composed of atypical, neoplastic melanocytes. "The sublines of human melanoma (mS) and hepatoma (human HepG2 and rat McA RH 7777) cell lines were obtained by retroviral infection of the wild-type cells with the cDNA of the human retinoic acid receptor alpha (RAR alpha)." (PMID 9667638, 1998). "We previously identified two RARα/RXRα responsive elements (RARE) on SerRS promoter, which can be activated by retinoic acid 30,33 in melanoma cells." (PMID 32550907, 2020). "For example, berberine can suppress EMT in melanoma cells by regulating cross-talk between PI3K/AKT and RARα/RARβ signaling." (PMID 31772677, 2019). "In the previous experiments with melanoma and hepatoblastoma human cells we have shown that constitutive expression of MDR1 gene was increased after RARα transfection in both RARα transformed cell sublines." (PMID 15910691, 2005). "In our previous study we found that RARα overexpression did not change Pgp functional activity in two RARα transformed sublines of human cells (melanoma and hepatoblastoma) but did change it in the rat cells." (PMID 15910691, 2005).